DEDD (death effector domain containing)
Description:
A scaffold protein that directs CASP3 to certain substrates and facilitates their ordered degradation during apoptosis. May also play a role in mediating CASP3 cleavage of KRT18. Regulates degradation of intermediate filaments during apoptosis. May play a role in the general transcription machinery in the nucleus and might be an important regulator of the activity of GTF3C3. Inhibits DNA transcription in vitro (By similarity).
Synonyms: DEDPRO1; DEFT; KE05; FLDED1; CASP8IP1; DEDD1; FLDED-1
Tractability: PROTAC: UniProt records ubiquitination sites on it; ubiquitination databases record sites on it.
Gene: Protein-coding gene on chromosome 1 (161,120,973 to 161,133,280, reverse strand). Ensembl gene ENSG00000158796.
Subcellular location: Cytoplasm; Nucleus, nucleolus
Subcellular location (Human Protein Atlas): Nucleoli; Nucleoplasm; Cytosol
Gene Ontology:
Molecular function: protein binding; DNA binding
Biological process: extrinsic apoptotic signaling pathway via death domain receptors; spermatogenesis; apoptotic process; developmental process involved in reproduction; regulation of apoptotic process
Cellular component: cytosol; cytoplasm; nucleolus
Genetic constraint (gnomAD): Loss-of-function variants: 3 observed, 30.35 expected, observed/expected ratio (o/e) 0.0989, 90% interval 0.044 to 0.25. The upper end of that interval is the gene's LOEUF score, 0.25, which puts it in group 1 of 6, group 1 being the genes least tolerant of losing a copy. Missense variants: 261 observed, 440.76 expected, observed/expected ratio (o/e) 0.59, 90% interval 0.53 to 0.66. Synonymous variants: 152 observed, 171.08 expected, observed/expected ratio (o/e) 0.89, 90% interval 0.78 to 1.02.
Homologues: Orthologues: chimpanzee DEDD (99% identical), dog DEDD (99% identical), macaque DEDD (99% identical), rabbit DEDD (99% identical), mouse Dedd (99% identical), guinea pig DEDD (98% identical), pig DEDD (98% identical), rat Dedd (98% identical), tropical clawed frog dedd (84% identical), zebrafish dedd (75% identical). Paralogues in human: DEDD2 (42% identical).
Diseases named in the same sentence as DEDD in open-access papers:
DEDD is named in the same sentence as 12 diseases in open-access papers, as found by Europe PMC text mining. Sharing a sentence is not in itself a finding about the gene and the disease. The quoted sentences say what the papers report.
diabetes (1 paper, 2013). "Similarly, the gene product known as phosphoprotein enriched in astrocytes 15 kDa/phopsphoprotein enriched in diabetes (PEA-15/PED) is a death effector domain-containing protein that modulates TNF-α-induced apoptosis in astrocytes." (PMID 23533150, 2013).
gastritis (1 paper, 2019). Inflammation of the stomach. "Among these, 519 genes were significantly increased in gastritis patients, including DedD protein, threonine aldolase and N-acetylmuramoyl-l-alanine amidase." (PMID 30478535, 2019).
pituitary tumours (1 paper, 2015). "miR-212 is shown to be strongly upregulated in pituitary tumours and a study suggested death effector domain-containing protein (DEDD) as its potential target." (PMID 26064134, 2015).
infection (2 papers, 2020 to 2024). The state of being infected such as from the introduction of a foreign agent such as serum, vaccine, antigenic substance or organism. "In separate infection experiments, the ΔdedD strain produced filaments visually indistinguishable from WT on dispersal, further suggesting that dedD plays a role in maintaining growth rate or survival during dispersal rather than directly controlling infection-related filamentation (IRF)." (PMID 39287381, 2024). "Interestingly, we found that dedD has an important role during dispersal from host cells, which was verified by our fluorescence-based competitive infection assay." (PMID 39287381, 2024). "We further demonstrate that the SPOR domain-containing protein DedD involved in peptidoglycan remodeling is required during UPEC dispersal from bladder cells and likely plays a role in stabilizing the bacterial envelope during host cell stress in the latter stages of the infection cycle." (PMID 39287381, 2024). "Since YtfB and DedD both have extracytoplasmic glycan-binding capacities, we speculate that these proteins play roles in stabilizing peptidoglycan and cell division or the cell envelope during envelope stress or conditions experienced by UPEC in the latter stages of the infection cycle." (PMID 39287381, 2024).
DEDD also shares sentences with these, for which no sentence is quoted: acute coronary syndrome (1 paper); cancer (1); colon cancer (1); colorectal cancer (1); heart failure (1); triple-negative breast carcinoma (1); tumor (1); urinary tract infection (1).